CCR7 (C-C motif chemokine receptor 7)
Diseases named in the same sentence as CCR7 in open-access papers (continued):
Sharing a sentence is not in itself a finding about the gene and the disease.
cancer (continued). "Our results confirm that CD8+ T-cells, when treated with MEKi and nivolumab in vitro, become T-cells with high, stable CCR7 expression, are resistant to the cytotoxic effect of cancer cells, and are distinct from naive T-cells." (PMID 36555420, 2022). "Homoplastically, miR-199a-5p, let-7a, and let-7e-5p were also confirmed to be able to target Ccr7 mRNA and control the metastasis of cancer cells, despite their impact in DC migration being still indistinct." (PMID 35281921, 2022). "Intriguingly, CCR7+LAMP3+ cDCs have been recently reported in cancer and have been characterized as mature DCs with a high potential for migration." (PMID 35618758, 2022). "In this section, expression of CCR7 during cancer initiation, progression, metastasis and at diagnosis will be discussed." (PMID 35203305, 2022). "When these cells were injected into the lumbar region of athymic nude Balb/c mice, cancer invasion and metastasis to lymph nodes was reduced, when compared to control cells with 4-fold higher levels of CCR7 expression." (PMID 35203305, 2022). "As observed with breast and gastrointestinal cancers, the cancers of the gastrointestinal tract have inconsistent responses to overexpression of CCR7." (PMID 35203305, 2022). "Overall, data supports roles for miRNA playing an important role in controlling CCR7 expression and cancer progression." (PMID 35203305, 2022). "CCR7 also facilitated cancer cell survival via PI3K activation, phosphorylation of mTOR and Akt pro-survival responses." (PMID 35203305, 2022). "In one case, immune response, CCR7 activity is typically beneficial, whereas in another other case, cancer spread, CCR7 responses are detrimental to the individual." (PMID 35203305, 2022). "CCR7 has been found mostly in the cytoplasm of cancers when evaluated by immunohistochemical analysis." (PMID 35203305, 2022). "The aim of this study was to assess the expression of CCR7/CCL19 in cancer tissue in relation to that of miRNAs (miR-let-7a, miR-335) as transcriptional regulators." (PMID 35160116, 2022). "Antagonizing these receptors and/or ligands provided novel platforms for cancer therapeutics: CCR7/CCL21 for lymph node metastases, and CXCR4/CXCL12 for lung, liver, bone marrow and brain metastases." (PMID 35203305, 2022). "Immunohistochemical staining of patient cancer samples revealed heterogeneous expression of CCR7, CXCR4 and CXCR6 with low expression in most primary tumors and strong chemokine receptor expression in metastatic lesions to the liver." (PMID 35203305, 2022). "In vitro, the established highly invasive cancer cells with high and low levels of CCR7 and let-7a expression, respectively, exhibited a greater invasive ability than the wild-type cell line." (PMID 36243683, 2022). "Chemokine ligand 19 (CCL19) is one of the ligands of chemokine receptor 7 (CCR7) and plays an important role in cancer." (PMID 36510567, 2022). "Simultaneously, VEGF-C also enhanced the expression of Ccl21 in the lymphatic endothelium to promote the entry of Ccr7+ cancer cells into the SLN." (PMID 36266717, 2022). "The microRNA (miRNA) let-7a suppresses migration and invasion of various types of cancer cells by downregulating CCR7 expression." (PMID 36243683, 2022). "Since under homeostatic conditions, CCR7 promotes migration of immune cells to lymph nodes, questions immediately arose regarding the ability of CCR7 to direct migration of cancer cells to lymph nodes." (PMID 35203305, 2022). "Future studies should focus on defining mechanisms that differentially regulate the unfavorable or beneficial role that CCR7 plays in cancer pathophysiology, to be able to improve outcomes in patients who harbor CCR7-positive cancers." (PMID 35203305, 2022). "Similar results were observed for another microRNA, miR-1275, when transfected into PCI-37B cells, which also elevated CCR7, leading to more aggressive cancer cell characteristics." (PMID 35203305, 2022).
cancer (continued). "Although different markers were used to evaluate EMT in cancers, there was a consistent CCR7-induced increased activation of Slug, N-cadherin, TGF-β, vimentin, phospho-ERK, phospho-Akt, MMP-2, MMP-9 and Snail attenuation of E-cadherin." (PMID 35203305, 2022). "The literature since 2000 was examined to determine to what extent the expression of CCR7 in malignant tumors promoted migration to the lymph nodes." (PMID 35203305, 2022). "Several malignant tumors, such as lymphomas, breast, prostate, gastric, and colon cancer, show increased expression of CCR7." (PMID 34830848, 2021). "Studies have shown that CCR7 expression is elevated in response to hypoxia conditions and different types of cancer." (PMID 35069589, 2021). "Through Pearson’s correlation coefficient analysis (|R2|> 0.3 and P< 0.05), 206 transcription factors were associated with cancer driver gene expression, and DDX3X, JAK1, EGR2, IKZF3, and CCR7 were the five most enriched cancer driver genes." (PMID 34507558, 2021). "The involvement of this protein in lymph node metastasis in cancer marks CCR7 as a penitential drug target." (PMID 34770763, 2021). "CCL21 was upregulated in lymphangiogenic sprouts, possibly recruiting CCR7 expressing cancer cells toward the lymphatic vessels." (PMID 34671596, 2021). "Most importantly, both CXCR4 and CCR7 have been proposed to be potential therapeutic targets in cancer treatments." (PMID 34685420, 2021). "We revisit the binary role that CCR7 plays in combatting and progressing cancer, and we discuss how CCR7 and DCs can be harnessed for the treatment of cancer." (PMID 34361107, 2021). "CCR7-induced integrin activation and metalloprotease secretion are processes that in other CCR7-expressing blood cancers are known to be required for CCR7-mediated TEM and for homing." (PMID 34778050, 2021). "It is worth mentioning that CXCR3, CCR7, and IL10 have been reported to be the underlying mechanisms in cancer metastasis-induced BCP in human." (PMID 34025351, 2021). "LXR/oxysterol signaling has been reported to create an immunosuppressive microenvironment favoring cancer progression by inhibiting the functional up-regulation of the chemokine (C-C motif) receptor-7 (CCR7) on the surface of maturing dendrocytes (DCs)." (PMID 33252713, 2021). "The overexpression of CCR7 appears to correlate both with LN metastasis in various cancers (breast, pancreatic, esophageal, lung, etc.), as well as a poorer survival prognosis." (PMID 34361107, 2021). "Lastly, we revisit the binary role CCR7 plays in combatting and progressing cancer, and we discuss how CCR7 and DCs can be harnessed for the treatment of cancer." (PMID 34361107, 2021). "This antibody neutralizes receptor-ligand interactions thus inhibiting CCR7-induced cell functions, such as the access of cancer cells to niches where CCR7 ligands are produced (e.g. LN or spleen)." (PMID 33841445, 2021). "We observed that the CD103loCD11b+ population expresses higher CCR7 levels than the other DC populations in both cancer models, suggesting a strong potential for trafficking to the lymph nodes and T cell interactions." (PMID 34847189, 2021). "Together, these findings support the existence of a functional and phenotypic diversity as a result of a biased signaling of CCR7 in homeostasis and blood cancers." (PMID 34778050, 2021). "A number of studies have demonstrated the pro-tumoral effect of CCR7 in several carcinomas including HCC." (PMID 34122408, 2021). "In the adipose tissues surrounding the lymphnode, β-caryophyllene reduced M2 macrophages and blocked the CCL19-CCL21/CCR7 axis, a signaling pathway important for recruitment of CCR7-expressing cancer cells or leukocytes to lymphnodes." (PMID 32948083, 2020). "In lymphangiogenesis, cancer cells penetrate lymphatic vessels where a cancer cell with CCR7 expression is kept in a lymph node, which is related to the high expression of a ligands for this receptor in these peripheral lymphoid organs." (PMID 33076281, 2020).
cancer (continued). "Studies involving the inhibition of CCR7 expression on cancer cells are yet to be explored at both the in vitro and in vivo level." (PMID 32340161, 2020). "Several chemokines and their receptors are overexpressed in cancer and strictly related to cancer progression and metastases such as CCR7, CXCR4 and CXCR7." (PMID 32283655, 2020). "CCR7 determines a cancer stem cell phenotype through the Notch signaling pathway, and PIP belongs to the PI3K signaling pathway." (PMID 32318098, 2020). "The panel was based on a backbone mixture of dried antibodies (anti-CD3, anti-CD4, anti-CD8, anti-CD45RA, and anti-CCR7) to detect naïve/memory T cells, recognised as potential prognostic/predictive immunological biomarkers in cancer immunotherapies." (PMID 32322591, 2020). "Our group previously reported the immunohistochemical expression of CCR1, CCR3, CCR4, CCR5, CCR7 and CXCR4 in SCC of the head and neck (oral cavity, oropharynx and larynx), suggesting an important role of CCR5 and CCR7 in cancer progression." (PMID 31011147, 2019). "Such a cooperative effect is highly desirable for cancer therapies targeting CCR7, given that it allows for more opportunities to inactivate the receptor to prevent trafficking by chemokines and thus block metastasis through the lymphatic system." (PMID 31442409, 2019). "Recent investigations demonstrated that SDF-1 and CCL21 chemokines through their cognate receptors CXCR4 and CCR7, signals to mTOR pathway in other cancers." (PMID 30518812, 2019). "We detect both novel (CS-1 and CS-2) and clinically relevant (CXCR1-CXCR2 phase-II antagonist Navarixin) CCR7 modulators with implications for multi-target strategies against cancer." (PMID 31442409, 2019). "In cancer, CCR7-mediated trafficking leads to lymph node metastasis, suggesting the receptor as a promising therapeutic target." (PMID 31442409, 2019). "We demonstrate that fluorescently tagged CCL19 and CCL21 permit the visualization and quantification of chemokine gradients in real time, while CCR7-expressing leukocytes and cancer cells sense the guidance cues and migrate along the chemokine gradients." (PMID 30518137, 2018). "CCR7-expressing cancer cells are also recruited by CCL19 and CCL21 to metastasize in lymphoid organs." (PMID 30518137, 2018). "Under both oxygen tension conditions, adhesion was inhibited by pre-incubation of the cancer cells MDA-MB-231 in the presence of neutralizing anti-CCR7 antibodies which bound efficiently to MDA-MB-231." (PMID 28416768, 2017). "This participates to the understanding of the CCL21/CCR7 impact on the activity and aggressiveness of cancer stem/initiating cells in the hypoxic microenvironment." (PMID 28416768, 2017). "Its expression on cancer cells was first recognized on hematogenous malignancies, in which the connection between high CCR7 expression and lymphoid organ involvement was discovered." (PMID 28114889, 2017). "Both Hes1 mRNA and protein levels were significantly reduced in CCR7-null cancer stem cell-like populations, either sorted for CD24+CD29hi expression by FACS or selected through culturing as secondary mammospheres." (PMID 28137279, 2017). "CC-chemokine receptor seven (CCR7), a G-protein coupled receptor normally facilitating immune cells lymphatic homing, has recently been identified on several cancer cells in promoting invasion and lymphatic specific metastasis by mimicking normal leukocytes." (PMID 28114889, 2017). "This increased adhesion effect which was displayed after CCL21 treatment only in hypoxia, was totally inhibited upon blocking the CCR7 receptors on the MDA-MB-231 cancer cells by pre-incubation with anti-CCR7 neutralizing antibodies." (PMID 28416768, 2017). "CC-chemokine receptor 7 (CCR7), which plays an important role in cell directional movement, is highly expressed in various cancers and positively related to lymph node metastasis." (PMID 27009073, 2016).
cancer (continued). "When stimulated by CCL21, CCR7 on cancer cells is proposed to regulate MMP-9 and promote lymph node metastasis." (PMID 27136535, 2016). "In contrast, some reports show that CCR7 expression on CRC cells themselves plays an important role in cancer progression." (PMID 27136535, 2016). "For example, CCR7-positive cancer cells metastasize to LNs where CCL19 and CCL21, the ligands for CCR7, are produced." (PMID 28123388, 2016). "This large difference among the cell lines was also seen in other studies in which the level of CCR7 expression of another ESCC cell line or other cancer cell lines was investigated." (PMID 24766770, 2014). "Under normal conditions, CCR7 is predominately expressed by T cells, B cells, and dendritic cells; however, its expression was also observed in several cancers and cancer cell lines where it is thought to promote cell survival and lymphatic metastasis." (PMID 24478703, 2014). "It is well known that CCR7-expressing cancer cells exhibit high lymphatic invasion ability due to the chemotactic effect of its ligands CCL19 and CCL21 which predominantly expressed in lymphatic endothelial cells." (PMID 24915301, 2014). "Chemokine (C-C motif) receptor 7 (CCR7) is involved in lymph-node homing of naive and regulatory T cells and lymphatic metastasis of cancer cells." (PMID 24915301, 2014). "In combination with CD28 in a so-called “third generation” CD28-OX40 CAR, combined costimulation improved survival and cytolytic activities of CCR7− T cells toward targeted cancer cells." (PMID 23761793, 2013). "Using recursive partitioning statistics, we showed that the frequency of 28% CD8+CCR7+ T cells in the blood discriminated cancer patients from NC with a high degree of accuracy." (PMID 23730621, 2013). "Second, CCR7− T cells persist in peripheral lesions due to their inability to re-enter the lymph, thereby increasing the probability for successful cancer cell killing." (PMID 23761793, 2013). "While naïve T cells express several chemokine receptors, including CXCR4 and CCR7, CCR7 is uniquely important in driving the homing of cells to lymph nodes, including naïve T cells, dendritic cells, and cancer cells." (PMID 24250818, 2013). "Recent studies have shown that both let-7a and CCR7 influence cell proliferation, as well as cancer cell invasion and migration." (PMID 22251626, 2012). "Since CCR7 was highly expressed in NPC sphere-forming cells and correlated with lymph node metastasis in various human cancers, we then determined the association of CCR7 expression with the clinical parameters in 39 primary NPC cases." (PMID 23285037, 2012). "The results suggest that CCL21 triggers the activation of CCR7 signaling through CCL21 secreted from cancer cells in an autocrine manner." (PMID 22251626, 2012). "Information garnered from this study lends insight to the mechanisms of survival of CCR7-mediated cancer cells and has implications for treatment targets in NSCLC." (PMID 21698152, 2011). "Stimulation of CCR7 by its ligand CCL21 induces migration and invasion of CCR7-expressing cancer cells." (PMID 21548969, 2011). "Diverse functional studies investigating the influence of CCR7 expression and the activation by its ligand CCL21 were recently conducted, revealing that CCR7 is crucial for adhesion, migration, and invasion of CCR7-expressing malignant tumors." (PMID 21548969, 2011). "Several studies have documented that the activation of CCR7 is responsible for mediating survival of certain cancer cell lines by promoting migration and proliferation or by inhibiting apoptosis." (PMID 21698152, 2011). "Epigenetic drugs can affect many genes and multiple pathways, including some capable of inducing cancer cell migration and invasion, such as CCR7, CXCR4, uPA and ROS." (PMID 20856924, 2010). "Consequently, anti-CCR7 monoclonal antibodies (mAbs) have been developed as cancer therapeutic agents." (PMID 40028039, 2025).
cancer (continued). "Modulating the mechanisms that form and restrain CCR7+ DC perivascular immune hubs may improve cancer immunotherapy." (PMID 41421339, 2025). "•CCR7 is a promising target of antibody therapy for cancers." (PMID 40028039, 2025). "In cancers, CCR7 has been revealed as a critical molecule in lymph node metastasis." (PMID 40028039, 2025). "Ccr7+Ido1+ DCs within the immunity hubs identified in our current study not only showed expression similarity with CCR7+LAMP3+IDO1+CD274+ activated DCs or mregDCs identified in human cancers, but also showed similar spatial co-localization with CD4+ and CD8+ T cells." (PMID 39414763, 2024). "Of the two ligands of CCR7, CCL19, and CCL21, only CCL21 is associated with metastasis, contributing to lymphatic metastasis in pancreatic, lung, breast, and other cancers via ERK signaling." (PMID 39114657, 2024). "Further, cancer cells can upregulate the production of CCR7/8 and CXCR4/5, which interact to the corresponding receptors from the lymph node namely CCL1/21 and CXCL10/12 respectively, resulting in the migration of cancer cells to the lymphatic vessels by chemotaxis." (PMID 38940900, 2024). "Cancer cells expressing C-C chemokine receptor type 7 (CCR7) direct their movement toward CCL21." (PMID 39338413, 2024). "In consideration of factors highlighted in the previous sections, this may be due to the reduced effect on CCR7+ cancer cells as free ligands are sequestered." (PMID 38786066, 2024). "In human specimens, we demonstrated that patients suffering from preoperative cancer-associated pain had higher expression of the receptors CCR7 and CXCR3, respectively, than patients without cancer-associated pain." (PMID 37834436, 2023). "The chemokine CCL21 regulates immune and cancer cell migration through its receptor CCR7." (PMID 37664721, 2023). "CCR7 (C-C Motif Chemokine Receptor 7), a receptor of cytokines CCL19 and CCL21, is implicated in the homing of T cells in lymph nodes, and it has mostly been studied with regard to its proangiogenic effect on cancer cells through an increase in VEGF levels." (PMID 38153746, 2023). "Furthermore, CCR7+ expression is downregulated with aging, chronic inflammation, and experience of cancer treatment." (PMID 37250774, 2023). "As a result, approaches inhibiting lymph node metastasis through CCR7 antagonism might unintentionally hinder the immune response to cancer." (PMID 38008741, 2023). "This duality underscores the complexity of cancer therapy decision-making regarding the CCR7 axis." (PMID 37944262, 2023). "Validity from several studies has revealed that MMP-9 and CCR7 could be good predictors and reliable indicators of cancer metastasis." (PMID 37600570, 2023). "CCR7 expressed on the surface of cancer cells can direct malignant cells from the primary site into the lymphatic system by binding to appropriate signaling proteins, spreading in the body and eventually forming metastases in other tissues, which greatly increases the risk of death for patients." (PMID 35702353, 2022). "The invasive ability of cancer cells is affected by the expression of CCR7." (PMID 36243683, 2022). "Ccr7 mRNA is down regulated in response to radiation in dendritic cells and may influence cancer cell migration." (PMID 35986207, 2022). "Interestingly, however, we found that some studies point to the opposite role of CCR7; specifically, CCR7 is induced in some cancer cells and contributes to metastasis formation." (PMID 36425071, 2022). "Overall, CCR7 expression is typically low in this type of cancer." (PMID 35203305, 2022). "Apart from CCR7 as a prognostic marker in cancer, there were some shortcomings of the work." (PMID 35874608, 2022). "CCR7 is also induced on certain cancer cells and contributes to metastasis formation." (PMID 35563750, 2022). "A function examination of CCR7 in chemotaxis cells may also be helpful in understanding its function in cancer spreading." (PMID 35874608, 2022).